FOXP3 (forkhead box P3)
Diseases named in the same sentence as FOXP3 in open-access papers (continued):
Sharing a sentence is not in itself a finding about the gene and the disease.
tumor (continued). "As a fight-back mechanism, tumor cells produceCD4+CD25+FOXP3+ T-regulatory (Treg) cells from CD4+T cells by shedding multitude of chemokines." (PMID 38038865, 2023). "Analysis of clinical samples from 259 resected ICCA cases reveal a significant association between high CD73 expression and an increased proportion of FOXP3+/CD8+ TILs and CD163+/CD68+ tumor-associated macrophages (TAMs)." (PMID 38213535, 2023). "CD4+, CD25+, and FoxP3+ Tregs play an essential role in tumor immune tolerance and failure of immunotherapy by secreting immunosuppressive cytokines such as TGF-β and IL-1015." (PMID 38008819, 2023). "CD4+Foxp3+ regulatory T cells (Tregs) are central regulators of anti-tumor immune responses and they represent a major cellular mechanism of tumor immune evasion." (PMID 36865537, 2023). "Regulatory T cells overwhelm conventional T cells in the tumor microenvironment (TME) thanks to a FOXP3-driven metabolic program that allows them to engage different metabolic pathways." (PMID 36045586, 2023). "FOXP3 was found to co-localize with tumor-infiltrating CD20+CD27+ B cells to promote effector and memory T cell differentiation and enhance B cell and NK cell activation and function." (PMID 38067301, 2023). "For example, sorafenib treatment increases intratumoral infiltrating of F4/80+ tumor-associated macrophages, CD4+CD25+FoxP3+ regulatory T cells, CCL2+/CCL17+ tumor-associated neutrophils and CD11b+Gr-1+ myeloid cells in human and murine HCC models." (PMID 36906597, 2023). "In tumor tissues, Tregs can be generated from local FOXP3- conventional T cells and/or recruited to the tumor site upon previous expansion in lymphoid organs." (PMID 37990034, 2023). "For instance, knockdown of WNT5A in melanoma xenografts in mice resulted in a in a lower number of Foxp3+ regulatory T cells (Treg) in the tumors as well as in tumor-draining lymph nodes." (PMID 36982422, 2023). "As expected, human naïve CD4+ T cells induced Foxp3+ Tregs generation in the tumor microenvironment." (PMID 36814928, 2023). "Our study showed that MTE reduced TGF-β1 secretion from cancer cells and FOXP3 expression in T lymphocytes in vitro and in vivo, impairing the immune escape ability of tumor cells." (PMID 37649480, 2023). "HPV-related cancers proliferate due to poor CD4+-mediated cytokine secretion, CD8+-associated cytotoxicity, and tumor penetrability, along with a high influx of regulatory CD4+ FOXP3+ T cells." (PMID 37513985, 2023). "Depletion of α-SMA + CAFs can impede cancer cell dissemination and tumor angiogenesis in BC and PDAC models and is associated with increased disease aggression and progression by enhancing CD3 + Foxp3 + Treg infiltration in the TME." (PMID 37723510, 2023). "The enhanced antitumor efficacy of FOXP3-overexpressing CD8 T cells was also verified using Pmel cells in B16F10 tumor-bearing mice." (PMID 36045586, 2023). "Immunological changes in the spleens of tumor-bearing mice were comparable between the 2 models but the baseline frequency of regulatory T cells (CD25+FoxP3+CD4+ T cells) was higher in the EO771 model." (PMID 36757800, 2023). "As described in the results, BC with a TN subtype expressing a higher level of GPR81 tended to exhibit attenuated anti-tumor immune response (lower ratios of CD8/FOXP3) in comparison with that expressing a lower level of GPR81." (PMID 37500811, 2023). "Activation of EGFR pathways in NSCLC was associated with decrease in CD8+ TILs, but an increase in tumor-infiltrating FOXP3+ Tregs." (PMID 37340370, 2023). "An IMC-based analysis of resection specimens from 12 patients with LUSC identified a novel population of CD3-CD4+FoxP3+CD25-CD127- cells in both tumour and adjacent regions of 10 patients, which were also TNF-α-positive and IFN-γ-negative." (PMID 37835491, 2023). "MTE treatment reduced FOXP3 expression in the TILs, inhibiting Treg differentiation in the tumor microenvironment in CAC mice." (PMID 37649480, 2023).
tumor (continued). "We also found that the relative frequency of regulatory T cells (FoxP3+CD4+ T cells) was higher in FN-positive tumor tissues than in those FN-negative tumors in the analysis of CD4+ T cells (P=0.0014)." (PMID 36960042, 2023). "In other words, in terms of expression level, FOXP3-positive T cells have completely opposite effects on tumor prognosis, which is why FOXP3-positive T cells were analyzed separately by expression level in this study." (PMID 37573372, 2023). "Tumor cells secrete a great number of cytokines that induce the sustained expression of Foxp3, resulting in immunosuppression." (PMID 36776832, 2023). "Next, we quantified the proliferating bona fide cytotoxic CD3 (GZMB+), FOXP3+, CD11c+ immune cells, and tumor cells (Pan-CK+) in the stroma and tumor areas by staining for the proliferation marker Ki67." (PMID 37349318, 2023). "On the other hand, the activation of OX40 can trigger additional anti-tumoral signaling promoting Bcl-xL and Bcl-2 expression, essential for long-term T-cell survival and elimination of the tumor suppressive activity of regulatory FOXP3+CD25+CD4+ T cells." (PMID 37719008, 2023). "The absolute number of Tregs was hardly decreased (CCR4−/−: 100 ± 21 FOXP3+ cells per 1 × 105 tumor cells vs. WT: 151 ± 29 FOXP3+ cells per 1 × 105 tumor cells; n = 9, p = 0.175), with a mean absolute reduction of 51 ± 36, (42.1%)." (PMID 37371612, 2023). "We performed Treg-labeled Foxp3 immunofluorescence staining on tumor tissues of 60 patients with UCEC to confirm the effect of DDC on immune cell infiltration." (PMID 37872211, 2023). "Based on the cut-offs of CD8 and FOXP3 in the tumor center and the invasive front, cases were divided into the high infiltrative group and the low infiltrative group." (PMID 37573372, 2023). "As a prognostic indicator, FOXP3+ regulatory T cells seem to negatively affect OS depending on each tumor site, the molecular subtypes, and tumor stages." (PMID 37173887, 2023). "The relevance of Tregs in tumor progression is highlighted by recent studies reporting a strong correlation between high infiltration of the TME with FoxP3+ Tregs and poor prognosis in hepatocellular, ovarian, and gastric cancers." (PMID 38313431, 2023). "Tumours harbouring PD-L1+ TILs were also the ones displaying higher CD4+/FOXP3+ (49.0 vs. 8.2 cells/mm2, p = 0.002) and CD8+/PD-1+ TIL cell density (40.8 vs. 12.3 cells/mm2, p = 0.016)." (PMID 37274775, 2023). "Anti-tumour and oncogenic properties have been attributed to FOXP3 depending on the cellular context and interacting partners." (PMID 36973425, 2023). "These FOXp3-positive cells are widely present in the tumor immunosuppressive microenvironment and promote the differentiation of Treg cells." (PMID 36759842, 2023). "In an animal model of cancer, Gilboa and colleagues first described FoxP3-based vaccination induction of FoxP3-specific T cells that eliminated FoxP3+ Tregs while enhancing anti-tumor immunity." (PMID 36175673, 2023). "NIR-PIT using an antibody–photoabsorber conjugate that targets CD25 selectively depletes the CD4+CD25+Foxp3+ Tregs infiltrating the tumor microenvironment and activates CD8+ T cells and natural killer (NK) cells, resulting in local anti-tumor immunity." (PMID 36839882, 2023). "The immune microenvironment was characterized by moderate infiltration of M2-like tumor-associated macrophages (TMAs) with positivity of CD163, CSF1R, CD85A (LILRB3), and PD-L1; moderate PD-1 positive T cells, and low FOXP3 regulatory T lymphocytes (Tregs)." (PMID 36975733, 2023). "In evaluating tumor immunity within the tumor bed, a relationship between high PD-L1+ cancer cells and the number of FoxP3+ Tregs was significantly detected." (PMID 37668710, 2023). "Foxp3+ cells have immunosuppressive properties that can interfere with beneficial anti-tumor immunity, enabling tumors to elude the host antitumor immune response." (PMID 36766393, 2023).
tumor (continued). "Another clinical investigation also showed a correlation between the frequency of Foxp3 + Tregs and tumor stage for patients with OSCC." (PMID 37221555, 2023). "In the IHC analysis, lower numbers of CD3+ and Foxp3+ cells were observed in tissue sections taken from untreated areas of the neoplasm." (PMID 37680007, 2023). "Though a tendency for high PD-L1 expression in lung tumors related to higher tumor-infiltrating FOXP3+ Treg counts was observed." (PMID 37340370, 2023). "Different subgroups of background ICs, including tumour-associated macrophages (TAMs), were assessed and scored for CD4, CD8, FOXP3, and CD163 expression." (PMID 38175373, 2023). "The findings from this study showed that infiltration of Foxp3 + Tregs in the tumor can predict poor disease-free survival for these patients." (PMID 37221555, 2023). "Lnc-EGFR is highly expressed in tumor-infiltrating lymphocytes, and its expression is positively related to Treg content, Foxp3 expression, and tumor size, but negatively related to IFN-γ expression." (PMID 38933287, 2023). "Further, it was reported that cells with low FOXP3 expression promote anti-tumor immunity, while cells with high FOXP3 expression inhibit anti-tumor immunity." (PMID 37573372, 2023). "In agreement with our previous data, overexpression of FOXP3 markedly increased the presence of transferred CD8 T cells within the tumor." (PMID 36045586, 2023). "This led to activation of the CXCL10-CXCR3 chemotactic chemokine axis and promotion of an antitumor immune response, while suppressing the tumor-promoting FoxP3+ CD4+ T cells." (PMID 37035245, 2023). "Overall, these results indicate a role of myeloid-ILK in tumour promotion through regulation of the tumour-infiltration of T cells either by restraining tumour-suppressing CD8+ T cells or by enhancing tumour-promoting FOXP3+ T cells." (PMID 38077324, 2023). "ICP-targeted mAbs aim to stimulate CD8 + and CD4 + FoxP3- anti-tumor T-cells while inhibiting immunosuppressive CD4 + FoxP3 + regulatory T-cells." (PMID 38057799, 2023). "According to TCGA database, strong infiltration of CD8+ T cells, CD4+ T cells and regulatory T cells (FoxP3) is noticed in the tumor microenvironment of UM patients expressing high levels of VISTA." (PMID 37662962, 2023). "Our study demonstrates the ratios of CD8/FOXP3 correlate with the tumour burdens in both AOM/DSS and APCmin/+ models, indicating an impact of myeloid-ILK deficiency on the differential tumour-infiltration of T cells." (PMID 38077324, 2023). "Taken together, we suggest that the collagen from the fibroblasts interacts with Tregs, inducing LAIR2 and FOXP3 expression and providing a favorable microenvironment for tumor progression." (PMID 36828832, 2023). "Samples were grouped according to DDR1 expression (low, <50% vs. high, ≥50% or low, <25% vs. high, ≥75%) and were compared to FoxP3, a nuclear transcription factor present in Tregs that represents the main tumor-promoting CD4+ T-cell population." (PMID 38136314, 2023). "FOXP3+ T cells express low levels of cytokines in the tumor microenvironment, which contributes to tumor immune evasion." (PMID 37345200, 2023). "Recent experimental data have suggested Tregs derived from CD4 + T cells or Treg subsets can be eliminated in the tumour environment by immunotherapy that is aimed at blocking Foxp3, together with the selective inhibition of other minor Treg subsets." (PMID 37670247, 2023). "It is worth noting that S15+ tumor cells were closer proximity to CD4+FoxP3+ Tregs compared with S15− tumor cells." (PMID 37674198, 2023). "Consistently, phenotypic and transcriptional profiling of the tumor and normal-tissue Tregs exhibited that these cells were Foxp3+Helios+ cells with high levels of inhibitory molecules (PD-1 and CTLA-4) and were associated with poor prognosis." (PMID 37835465, 2023).
tumor (continued). "Using linear regression analysis, we assessed the association of CD20+, CD8+, CD4+, FOXP3+ TIL-subtypes and CD4+/CD8+, FOXP3+/CD8+ ratios with the expression of HIF1α, LDH5, VD (t1, t2 and t3) and VSA (t2 and t3) in the invading tumor front." (PMID 36900270, 2023). "In the TME, interaction between PD-L1, CD8+ TILs, tumor-infiltrating FOXP3+ regulatory T lymphocytes (Tregs) was also reported." (PMID 37340370, 2023). "FOXP3, a critical transcription factor involved in the biology of regulatory T cells, has been detected as highly expressed in the tumor cells of CC patients." (PMID 36672296, 2023). "Flow cytometry analysis showed an increased ratio of CD8+ T cells to FoxP3+ regulatory T cells (Tregs) in the tumor upon treatment with domatinostat." (PMID 36920329, 2023). "Low infiltration of cells that highly express (high-intensity) FOXP3 was found to be a significantly poor prognostic factor in the tumor center (p = 0.0458) (c)." (PMID 37573372, 2023). "FOXP3+ expression was frequently observed in tumor and peri-tumoral compartments compared to normal pancreatic parenchyma (13.8 vs. 2, p < 0.001)." (PMID 37366900, 2023). "FoxP3 expression increased in tumor-infiltrating T-lymphocytes (TIL) after co-culture with syngeneic GB-CIITA." (PMID 38201622, 2023). "Tumor-associated macrophages (CD68, CD163), cytotoxic T cells (CD8), and regulatory T cells (FoxP3) were quantified via three methods." (PMID 37543970, 2023). "Researchers further analyzed that T cells isolated from the tumors of mice bearing SCLC, CD4+ TILs, and CD8+ T TILs were observed to infiltrate the tumor, while few FOXP3+ TITLs gather in the tumor bed." (PMID 36776832, 2023). "We found that the frequency of CCR8+ CD25+ FOXP3− Tconv cells inversely correlates with the frequency of tumor-infiltrating CD8+ T cells, suggesting that they play an inhibitory role in human tumor immunity." (PMID 38100544, 2023). "In our evaluation of tumour-infiltrating lymphocytes (TILs) and Foxp3 expression in tumour tissues using immunohistochemistry (IHC) in 358 patients, patients with high levels of CD4 + T cells or CD8 + T cells exhibited better prognosis (all p < 0.05)." (PMID 37582713, 2023). "An upsurge in Treg cells can facilitate tumor immune escape, while activation of FOXP3+CD25+CD4+ Treg cells can markedly dampen tumor immune response." (PMID 37920470, 2023). "In future, we will collect more CRC samples to confirm the infiltrations of CD66b+ TANs, Foxp3+ Tregs, and CD163+ TAMs being associated with tumor differentiation." (PMID 37232465, 2023). "We firstly tested immunologic markers of CD4+, CD8+, CD68+, FOXP3+, PD‐L1+, CD4+FOXP3+, CD4+FOXP3−, CD68+PD‐L1+, CD68+PD‐L1−, CD8+PD‐L1+, and CD8+PDL1− in the tumor core area, tumor‐associated stroma area, and total area before NAC." (PMID 36043478, 2023). "In assessing the impact of SOCS1 and PD-1 inactivation in transferred CD8+ T cells on the cellular composition of tumor, we observed depletion of Foxp3+ Tregs relative to sgOlf OT1s in mice treated with sgSocs1 OT1s, but not sgPD-1 OT1–treated animals." (PMID 38099496, 2023). "TGF-β mediated transformation of resting CD4+ T cells into FoxP3+ Treg cells; lead to tumor metastasis." (PMID 37868967, 2023). "Results from CC samples (n = 304) compared against normal tissue (n = 22) showed a significant increase in FOXP3 mRNA expression in tumor samples." (PMID 36672296, 2023). "TPST-1495 induced significant infiltration of tetramer-positive AH1-specific CD8+ T cells and CD4+ FoxP3− cells into the tumor and moderately increased CD49b+ natural killer (NK)-cell infiltration and the ratio of tumor CD8+ to Treg+ T cells." (PMID 37559947, 2023). "In particular, inhibiting USP22 by CRISPR in Treg cells has been demonstrated to lower Foxp3 protein production as well as reduce tumor growth in different tumor types." (PMID 37658402, 2023).
tumor (continued). "Combined RT with immunotherapy (OX40/TLR agonist) resulted in an approximately 1.5-fold decrease in Treg density and Foxp3 expression levels in tumor tissue." (PMID 37833255, 2023). "As one of the markers of the immunosuppressive tumor microenvironment, the proportions of regulatory T cells (CD4+Foxp3+ T cells, Tregs) in the tumor tissues of the saline and the Cap groups reached 134.2 and 98.16 per milligram of tumor, respectively." (PMID 37550297, 2023). "IL6-STAT3 is also known to downregulate Foxp3 expression and promote Tregs to Th17 cells conversion, which inhibits the immune suppression in the tumor microenvironment." (PMID 36875137, 2023). "Evidences also suggest that tumor-derived TGFβ is one of the major drivers for induction of CD4+CD25+FOXP3+ Treg cells from CD4+CD25− T cells." (PMID 38038865, 2023). "FoxP3+ T cells are usually associated with a negative regulatory function (Treg) over CD4+ Th cells, and their presence in the tumor microenvironment often indicates an immunosuppressive function toward anti-tumor T cells." (PMID 36993983, 2023). "Regardless, depleting FOXP3+ Treg cells from tumor tissues is an effective treatment for CRC and other malignancies, primarily because it alleviates immunosuppression." (PMID 36765047, 2023). "The immunohistochemical expression of CD8, CD4 and FOXP3 positive cells was evaluated in tumor tissue samples in relation to radiological treatment." (PMID 36717781, 2023). "The proportion of splenic FOXP3+ Tregs also showed a moderate but significant positive correlation with both serum Ca10 levels and tumor size." (PMID 37990034, 2023). "The percentage of intratumoural FOXP3+ T cells correlates with clinicopathological stages and high tumour grade." (PMID 36928373, 2023). "Statistical analysis suggested that elevated PD-1 and FOXP3 expressions were significantly correlated with tumor grade and increased mitotic index (P<0.05 for both the markers)." (PMID 37621817, 2023). "Since TGF-β is produced at high levels in the TME, it is likely that it favors the expression of Foxp3, not only in Tregs but also in tumor cells." (PMID 37766222, 2023). "LDH5 was directly related to high CD4+ TILs in the invading tumor front (p = 0.05, r = 0.26), while nuclear LDH5 expression was directly linked with FOXP3+ TILs (p = 0.01, r = 0.31) and FOXP3/CD8 ratio (p = 0.03, r = 0.27)." (PMID 36900270, 2023). "In CD8 and FOXP3 immunostaining, the number of expressing-infiltrating cells was determined by dividing the region into tumor center and invasive front areas." (PMID 37573372, 2023). "Although there is consensus on the tumor suppressive role of Foxp3 in the normal mammary gland, its involvement in the pathogenesis of BRCA remains controversial." (PMID 37766222, 2023). "Tumor‐related Foxp3+ Tregs were frequently detected in residual metastasis and primary tumor foci, while the decreased Foxp3+ Tregs were supposed to be associated with pathological remission and therapy effects." (PMID 36226375, 2023). "Among which, IL‐33 recognizes the receptor ST2 in Foxp3+ Tregs, then promoting the Foxp3+ Tregs accumulation and immunosuppressive functions in tumor." (PMID 36226375, 2023). "Some studies have explored the relationship between tumor cell differentiation and the infiltration of FoxP3+ Tregs, CD66b+ TANs, or CD163+ TAMs in the tumor microenvironment." (PMID 37232465, 2023). "scRNA-seq further revealed the presence of Foxp3+ Tregs and γδT17 cells, which contribute to an immunosuppressive tumor microenvironment (TME)." (PMID 37143122, 2023). "In our study, increased densities of PD-1+ cells in the tumor and FoxP3+ cells in the stroma were observed in patients with Amp11q13 compared with patients without Amp11q13." (PMID 37056769, 2023). "In inner tumor areas a direct association of CD4+, FOXP3+ TILs, and FOXP3+/CD8+ ratio with VSA t2 was noted (p = 0.008, 0.02, and 0.05, respectively)." (PMID 36586079, 2023).